ZNF252P-AS1 (ZNF252P antisense RNA 1)
Synonyms: C8orf77
Gene: Long non-coding RNA gene on chromosome 8 (145,002,811 to 145,037,152, forward strand). Ensembl gene ENSG00000255559.
Diseases named in the same sentence as ZNF252P-AS1 in open-access papers:
ZNF252P-AS1 is named in the same sentence as 2 diseases in open-access papers, as found by Europe PMC text mining. Sharing a sentence is not in itself a finding about the gene and the disease. The quoted sentences say what the papers report.
hepatocellular carcinoma (1 paper, 2022). A malignant tumor that arises from hepatocytes. "LncRNA ZNF252P antisense RNA 1 (ZNF252P-AS1) is located on chromosome 8, it is a novel identified lncRNA in hepatocellular carcinoma and might be an independent prognostic biomarker for hepatitis B virus-positive hepatocellular carcinoma patients." (PMID 34980214, 2022).
ovarian carcinoma (1 paper, 2022). A malignant neoplasm originating from the surface ovarian epithelium. "Our work aimed to study the specific functions of ZNF252P antisense RNA 1 (ZNF252P-AS1) in ovarian cancer." (PMID 34980214, 2022).